NDUFV3 (NADH:ubiquinone oxidoreductase subunit V3)
Description:
Accessory subunit of the mitochondrial membrane respiratory chain NADH dehydrogenase (Complex I), that is believed not to be involved in catalysis. Complex I functions in the transfer of electrons from NADH to the respiratory chain. The immediate electron acceptor for the enzyme is believed to be ubiquinone. May be the terminally assembled subunit of Complex I.
Synonyms: CI-9kD; CI-10k
Tractability: Small molecule: an approved drug acts on it; a structure with a bound ligand is known. Antibody: UniProt places it where antibodies can reach, with high confidence. PROTAC: its protein half-life has been measured.
Gene: Protein-coding gene on chromosome 21 (42,879,644 to 42,913,304, forward strand). Ensembl gene ENSG00000160194.
Subcellular location: Mitochondrion inner membrane
Subcellular location (Human Protein Atlas): Mitochondria
Pathways (Reactome):
Metabolism: Complex I biogenesis; Respiratory electron transport
Metabolism of proteins: Mitochondrial protein degradation
Gene Ontology:
Molecular function: protein binding; RNA binding; NADH dehydrogenase (ubiquinone) activity
Biological process: mitochondrial ATP synthesis coupled electron transport; aerobic respiration; mitochondrial electron transport, NADH to ubiquinone; proton motive force-driven mitochondrial ATP synthesis; proton transmembrane transport
Cellular component: mitochondrial inner membrane; mitochondrion; respiratory chain complex I
Genetic constraint (gnomAD): Loss-of-function variants: 45 observed, 39.56 expected, observed/expected ratio (o/e) 1.14, 90% interval 0.89 to 1.46. The upper end of that interval is the gene's LOEUF score, 1.46, which puts it in group 6 of 6, group 1 being the genes least tolerant of losing a copy. Missense variants: 580 observed, 607.6 expected, observed/expected ratio (o/e) 0.95, 90% interval 0.89 to 1.02. Synonymous variants: 235 observed, 248.68 expected, observed/expected ratio (o/e) 0.94, 90% interval 0.85 to 1.05.
Homologues: Orthologues: chimpanzee NDUFV3 (99% identical), macaque NDUFV3 (90% identical), mouse Ndufv3 (51% identical), rat Ndufv3 (49% identical), zebrafish ndufv3 (19% identical), rat Ndufv3-ps1 (14% identical).
Diseases named in the same sentence as NDUFV3 in open-access papers:
NDUFV3 is named in the same sentence as 21 diseases in open-access papers, as found by Europe PMC text mining. Sharing a sentence is not in itself a finding about the gene and the disease. The quoted sentences say what the papers report.
Down syndrome (2 papers, 2016 to 2017). "Third, NDUFV3 is located on chromosome 21 and so is upregulated in patients with trisomy 21 Downs syndrome." (PMID 27940020, 2017). "NDUFV3, which codes for a NHDH-ubiquinone oxidoreductase complex subunit, is overexpressed in Down syndrome and contributes to DS phenotype." (PMID 26848775, 2016).
clear cell renal cell carcinoma (1 paper, 2023). "When treating patients with clear cell renal cell carcinoma, NDUFV3 was found to be an independent predictor of overall survival, whereas FKBP11 has the potential to be an early marker for hepatocellular carcinoma." (PMID 36999050, 2023).
head and neck squamous cell carcinoma (1 paper, 2024). A squamous cell carcinoma that arises from any of the following anatomic sites: lip and oral cavity, nasal cavity, paranasal sinuses, pharynx, larynx, and salivary glands. "In TCGA, all tumor samples with diverse human cancer types, a significant negative correlation between PTBP1 expression and exon skipping of NDUFV3 was also observed in combined 33 cancer types, and the Head and Neck squamous cell carcinoma (HNSC) serves as a representative example." (PMID 39872664, 2024).
Sepsis (1 paper, 2025). Sepsis is defined as life-threatening organ dysfunction caused by a dysregulated host response to infection. "We assumed that another three cis-eQTL genes (PDK2, RPS18, and NDUFV3), which were negatively associated with sepsis-induced ARDS, could be targeted with potential drugs in ARDS treatment." (PMID 40116326, 2025). "Subsequent drug target analysis confirmed the role of four targets (PSMA4, PDK2, RPS18, and NDUFV3) as druggable genes for sepsis-related ARDS." (PMID 40116326, 2025). "We discovered potential drug targets for sepsis-related ARDS through a comprehensive analysis, among which four druggable targets (PSMA4, PDK2, RPS18, and NDUFV3) should be dialectically treated." (PMID 40116326, 2025).
cancer (3 papers, 2011 to 2024). A tumor composed of atypical neoplastic, often pleomorphic cells that invade other tissues. "These correlation data support the notion that PTBP1-mediated exon-skipping regulation of NDUFV3 is prevalent in diverse cellular senescence models and cancers." (PMID 39872664, 2024). "Multiple lines of evidence support that PTBP1-mediated exon skipping of NDUFV3 exists in various cellular senescence models and cancer types." (PMID 39872664, 2024). "Although no direct function for this gene product has been described in PCa, mitochondrial complex I, of which the NDUFV3 protein is a component, plays an important role in interferon-beta and retinoic acid-induced cancer cell death." (PMID 22194994, 2011). "In addition, patients with higher exon-skipping degree of NDUFV3 in their tumor samples not only have better survival rate in combined 33 cancer types but also in given cancer types such as HNSC." (PMID 39872664, 2024). "We also provide lines of evidence to support that the negative correlation between PTBP1 and exon skipping of NDUFV3 exists in other cellular senescence models and diverse cancers, indicating the universality of such splicing regulation mechanism and functional regulatory relationship." (PMID 39872664, 2024).
tumor (3 papers, 2020 to 2024). "Further studies about the relationship of SDHC, SDHD, MTCO3, and NDUFV3 in MQ-induced anti-tumor effect will be applied." (PMID 32850358, 2020). "ANKRD36BP1 (dist = 3,795), TBX19 (dist = 29815) chr1:168220463A > I (p < 0.001), HOOK3 chr8:42883441A > I (p = 0.0011), PGPEP1 chr19:18476416A > I (p < 0.001), and NDUFV3 chr21:44329452A > I (p = 0.038) were significantly different between tumor and normal tissues." (PMID 36999050, 2023). "Tumor showed upregulation of HOOK3 chr8:42883441A > I, PGPEP1 chr19:18476416A > I, and NDUFV3 chr21:44329452A > I, as compared with normal tissue." (PMID 36999050, 2023).
mitochondrial disease (2 papers, 2017 to 2022). "First, four mutations in NDUFV3 have been observed in patients with mitochondrial disease, although they have not been confirmed as causatory." (PMID 27940020, 2017).
infection (1 paper, 2021). The state of being infected such as from the introduction of a foreign agent such as serum, vaccine, antigenic substance or organism. "Our data suggest that elevated mtROS after infection results from downregulation of SIRT3 and consequently NDUFS7 and NDUFV3." (PMID 33531400, 2021).
neurodegenerative disease (1 paper, 2025). A disorder of the central nervous system characterized by gradual and progressive loss of neural tissue and neurologic function. "The mitochondrial dysfunction in the neurodegenerative diseases cluster (Cluster 4) comprises 95 genes, including several key mitochondrial protein genes acting as pivotal hub genes, such as Sdhb, Ndufa4, Ndufb4c, Ndufb4b, Ndufv3, Ndufa9, Ndufc1, Ndufs5, Ndufb4, Ndufa12, Ndufa11, and Ndufb1." (PMID 41294802, 2025).
NDUFV3 also shares sentences with these, for which no sentence is quoted: Alzheimer disease (1 paper); amnesia (1); cardiac hypertrophy (1); diabetes (1); epilepsy (1); heart failure (1); hepatocellular carcinoma (1); Leigh syndrome (1); leukemia (1); nervous system disorder (1); Parkinson’s (1); schizophrenia (1).